SF3B1 (splicing factor 3b subunit 1)
Diseases named in the same sentence as SF3B1 in open-access papers (continued):
Sharing a sentence is not in itself a finding about the gene and the disease.
mucosal melanoma (23 papers, 2017 to 2025). A melanoma that arises from a mucosal site. "SF3B1 is involved in RNA splicing, and the hotspot mutation recurrent in mucosal melanoma changes the splicing of several cancer genes, including the non-canonical BAF complex member BRD9." (PMID 35706047, 2022). "Amplifications of PAK1 and GAB2 were more commonly observed in acral melanomas, whereas SF3B1 R625 codon mutations were unique to mucosal melanomas (12.9%)." (PMID 35706047, 2022). "Three genes were enriched for mutations among mucosal melanomas in contrast to cutaneous melanomas: SF3B1 (27% vs. 2%), KIT (18% vs. 3%), and ATRX (9% vs. 1%)." (PMID 33724703, 2021). "The most frequent mutations in mucosal melanoma were in SF3B1 (27%), KIT (18%), and NF1 (17%), a pattern that is distinct from cutaneous melanomas." (PMID 33724703, 2021). "Recently, SF3B1 was identified as a significantly mutated gene in mucosal melanoma, especially in uveal, female genital and anorectal melanomas." (PMID 34102999, 2021). "Second, although SF3B1 has been reported as a frequently mutated gene in mucosal melanoma, only one (1/32, 3.12%) SF3B1 mutation with a recurrent somatic mutation at codon R625 was found in 32 samples in this cohort." (PMID 32984050, 2020). "We previously reported splicing factor SF3B1 as a significantly mutated gene in mucosal melanoma using OncodriveFML." (PMID 30847022, 2019). "Oncogenic driver events are also found in the majority (93%) of anorectal melanomas with NF1 in 20% of cases and SF3B1 mutations as a recurrent genetic event in mucosal melanomas." (PMID 31466283, 2019). "Molecular subgroups of mucosal melanoma with SF3B1 mutations occurred predominantly in the vulvovaginal region." (PMID 30847022, 2019). "Recently, we performed whole-genome sequencing (WGS) on a large cohort (n =183) of cutaneous (n = 140), acral (n = 35) and mucosal melanomas (n = 8), and SF3B1 (splicing factor 3B subunit 1) was identified as significantly mutated gene in mucosal melanoma." (PMID 30847022, 2019). "More recently, mutations in SF3B1 (particularly at codon 625) have been identified in various pigmented tumours, including UM, mucosal melanoma, leptomeningeal melanoma and blue naevi-like cutaneous melanoma." (PMID 30558566, 2018). "Other recent studies have reported the frequent occurrence (37%) of the SF3B1 gene of the spliceosome pathway in mucosal melanomas; in cutaneous melanomas, this gene is mutated in only 4% of cases." (PMID 29156643, 2017). "Concordant with prior reports, pathogenic SF3B1 mutations were found only in mucosal melanoma." (PMID 35706047, 2022). "SF3B1 mutation has been reported to be associated with late metastatization and better prognosis in patients with uveal melanoma; however, it did not seem to have the same correlation in a recently published case series of mucosal melanomas." (PMID 35008570, 2021). "SF3B1 mutation represents another promising target among patients with mucosal melanoma." (PMID 35008570, 2021). "Mutations that are noted in mucosal melanoma include neurofibromin 1 (NF1), KIT, and splicing factor 3b subunit 1 (SF3B1); NRAS and BRAF mutations occur at far lower rates than traditional cutaneous melanoma." (PMID 39001457, 2024). "At present, some studies have found that mutations that activate SF3B1 and KIT, the deletion of CDKN2A, PTEN, or SPRED1, and the amplification of CDK4, TERT, KIT, MDM2, or CCND1 are common in mucosal melanoma." (PMID 38065883, 2023). "These mutations have been observed previously in mucosal melanoma, particularly KIT and SF3B1 mutations." (PMID 33724703, 2021).
mucosal melanoma (continued). "Mucosal melanoma also frequently exhibits mutations in genes such as v-kit Hardy-Zuckerman 4 feline sarcoma viral oncogene homolog (KIT), neurofibromatosis (NF), and spliceosome factor 3b (SF3B1), with KIT specifically associated with vulvar melanoma." (PMID 39006602, 2024). "By comparison with cutaneous melanoma, mucosal melanoma has a decreased frequency of BRAF mutations (<10%) and an increased frequency of mutations of CD117 or c-KIT (40%), along with other somatic mutation (SF3B1, ATRX, ARID2, and SETD2)." (PMID 35334544, 2022). "Our data suggest that mutant KIT/SF3B1 co-occurrence may be a specific feature of a subset of mucosal melanomas including ConjMel, anorectal, and genitourinary melanomas." (PMID 34359736, 2021). "Common molecular drivers and mutations affecting spliceosomal components such as SF3B1 have been reported to be associated with disease outcome in some cancer types, but not in mucosal melanoma." (PMID 30847022, 2019). "In fact, alterations to driver genes such as SF3B1 and NF1 are relatively common in mucosal melanoma." (PMID 31466283, 2019). "However, mutations in other drivers of mucosal melanoma frequently seen in human patients, such as SF3B1 and ATRX, were not seen, suggesting that these canine cancers may not represent a faithful model for the subset of human mucosal melanoma patients with mutations in these genes." (PMID 32652526, 2020).
Myelodysplasia (18 papers, 2016 to 2026). Clonal hematopoietic stem cell disorders characterized by dysplasia (ineffective production) in one or more hematopoietic cell lineages, leading to anemia and cytopenia. "Here, we describe a young adult with GATA2 deficiency presenting with Legionella pneumonia, COVID-19, and HLH with underlying SF3B1-mutated myelodysplasia that responded successfully to allogeneic hematopoietic stem cell transplantation." (PMID 42130790, 2026). "The heterozygous Sf3b1K700E conditional knock-in mice has previously been shown to develop macrocytic anemia due to impaired erythropoiesis, myelodysplasia, and aberrant splicing, reflecting the phenotype of the SF3B1 mutation seen in MDS patients." (PMID 38997434, 2024). "SF3B1 mutations are seen in AML with myelodysplasia‐related changes, but with the low VAF (4.3% ⟶ 2.5%) and eventual disappearance on the 4/2024 myeloid NGS, its role in disease progression and loss of response to VEN‐based therapy remains unknown." (PMID 41439211, 2025). "Thus, U1 snRNA mutations have been associated with medulloblastomas, U2 SF3B1 mutations with blood cancers such as myelodysplasia or lymphocytic leukaemia, U5 Prp8 mutations with retinitis pigmentosa and QKI downregulation with lung cancer." (PMID 39273537, 2024). "In particular, the adverse-risk group has been expanded to include seven additional mutations: BCOR, EZH2, SF3B1, SRSF2, STAG2, U2AF1, and ZRSR2—together with ASXL1 and RUNX1 (already included in ELN 2017)—forming the “myelodysplasia-related” (MR) gene group." (PMID 41464583, 2025). "Males had a higher frequency of mutations in genes of the spliceosome complex (SF3B1, SRSF2, U2AF1 or ZRSR2) (19.1% vs. 5.7% in females; P = 0.002) and the nine myelodysplasia-related genes (31.6% vs. 17.9% in females; P = 0.015)." (PMID 38890297, 2024). "Only 5 were assigned to the adverse group because of myelodysplasia-related mutations (RUNX1, n = 2; BCOR, n = 1; SF3B1, n = 1; U2AF1, n = 1)." (PMID 37085611, 2023). "The presence of mutations in at least one gene associated with myelodysplasia (i.e., SRSF2, SF3B1, U2AF1, ZRSR2, ASXL1, EZH2, BCOR, or STAG2) was significantly more frequent in older patients." (PMID 35805006, 2022). "Seventy-nine patients, or 45% of all re-classified patients, were moved from ELN-2017 favorable (n = 11) or intermediate (n = 68) to ELN-2022 adverse risk based on the inclusion of additional myelodysplasia-related (MR) mutations (BCOR, EZH2, SF3B1, SRSF2, STAG2, U2AF1, ZRSR2) as poor-risk markers." (PMID 37041198, 2023). "Likewise, mutations in the snRNP components PRPF8, PRPF3, U2AF35, and SF3B1 cause diseases (e.g., retinitis pigmentosa for PRPF proteins, and myelodysplasia for U2AF35 and SF3B1) that are associated with broad changes in the production of splice variants." (PMID 28703423, 2017).
refractory anemia (18 papers, 2013 to 2025). "Of these different splicing factors, SF3B1 is one of the most frequently mutated genes, and mutations in SF3B1 have been found in more than 85% of patients with refractory anemia with RARS." (PMID 29433555, 2018). "For instance, SF3B1, which encodes an RNA-splicing factor and is orthologous to let-763/sftb-1, has mutations related to myeloid cancers and refractory anemias." (PMID 29339407, 2018). "Mutations in SF3B1 are associated with 80% cases of refractory anemia with ring sideroblast (RARS), a subtype of MDS." (PMID 28545085, 2017). "More than 85% of refractory anemia with ring sideroblast patients (RARS) contains mutations in SF3B1 gene with SF3B1K700E as the most frequent mutation." (PMID 28545085, 2017). "The presence of SF3B1 gene mutations is a hallmark of refractory anemia with ring sideroblasts (RARS)." (PMID 25955609, 2015). "In patients with MDS, SF3B1 mutations are prevalent (approximately 25 % in all MDS cases) and occurring in approximately 85 % of cases in a form of MDS (refractory anemia with ringed sideroblasts), with K700E the most frequently observed mutation." (PMID 38975181, 2024). "MDS with SF3B1 mutation (MDS-SF3B1) constitute a distinct subgroup of MDS, characterized by bone marrow accumulation of mutant dysplastic erythroblasts (ring sideroblasts), erythroid cytopenia, and refractory anemia." (PMID 40858805, 2025). "In contrast to the association of SF3B1 mutations with ringed sideroblast-containing subtypes of MDS, SRSF2 and U2AF1 mutations appear to be enriched in more aggressive subtypes of MDS, including the WHO subtypes refractory anemia with excess blasts I (RAEB I) and RAEB II." (PMID 27151974, 2016).
cutaneous melanoma (17 papers, 2013 to 2025). A primary melanoma arising from atypical melanocytes in the skin. "UM tumors are frequently detected with mutations in GNA11, GNAQ, EIF1AX, BAP1, and SF3B1 instead of the typical mutations associated with cutaneous melanoma." (PMID 40283643, 2025). "The goal of our study was to analyze if SF3B1 mutations not only play a role in uveal, but also in cutaneous melanoma." (PMID 23694694, 2013). "Taking these results together, the approach pinpointed well-established driver genes also detected by frequency-based methods, but also likely drivers not readily detected by such methods, giving further support for GNAQ, KIT and SF3B1 driver mutations in cutaneous melanoma." (PMID 36396655, 2022). "SF3B1 and KIT have been shown to have a higher mutation rate in MM as compared to cutaneous melanoma, whereas BRAF and NRAS have a lower mutation rate in MM." (PMID 39416390, 2024). "The most frequent mutations in MM have been in SF3B1 (27%), KIT (18%) and NF1 (17%), a different pattern from cutaneous melanomas." (PMID 38275835, 2024). "Mutations in KIT, NF1 and SF3B1 genes are more frequently seen in mucosal melanomas, while alterations to NRAS and BRAF genes are more common in cutaneous melanomas." (PMID 34209084, 2021). "Although targeted therapy has evolved in the last years and significantly improved the prognosis of patients with cutaneous melanoma, its use in vulvar and vaginal melanomas is still limited by the different mutagenic profiles involving fewer BRAF mutations and more c-KIT, NF1 and SF3B1 mutations." (PMID 34209084, 2021). "This argues against a major role for SF3B1 in tumorigenesis or progression of cutaneous melanoma." (PMID 23694694, 2013).
pancreatic cancer (15 papers, 2015 to 2024). "Splicing factor 3b subunit 1 (SF3B1) K700E mutation favored in vitro cell proliferation and in vivo tumor growth in pancreatic cancer cells." (PMID 37097392, 2023). "In this study, by loss‐of‐function and gain‐of‐function studies, we demonstrated that SF3B1 K700E mutation favored in vitro cell proliferation and in vivo tumor growth in pancreatic cancer cells." (PMID 33932092, 2021). "One subject with an SF3B1 mutation developed pancreatic cancer, the other subject harboring a U2AF1 mutation died due to a stroke." (PMID 32457355, 2020). "Recurrent mutations in the SF3B1 gene have been detected in several types of cancer such as UMs, breast and pancreatic carcinoma, and hematological diseases like CLL and MDS." (PMID 26769193, 2016). "Validating these findings, we found that genes encoding for the splice factors RBM10, SF3B1, and U2AF1 are also frequently mutated in the Pancreatic Cancer Canadian (PACA-CA) cohort." (PMID 37823551, 2023). "We demonstrate that IPMNs and MCNs are precursors of invasive pancreatic cancer, that alterations in ATM, GLI3, and SF3B1 are present in these lesions, and that SMAD4/TGFBR2 alterations are likely drivers of invasion in a subset of cases." (PMID 32796935, 2020). "A two-stage case-control study was conducted to examine the association between six candidate U2-depedent spliceosome genes (SRSF1, SRSF2, SF3A1, SF3B1, SF1 and PRPF40B) and pancreatic cancer (PC)." (PMID 26498691, 2015).
prostate carcinoma (13 papers, 2018 to 2025). A carcinoma that arises from epithelial cells of the prostate gland. "SF3B1 is overexpressed in prostate tumors and associates with aggressive features of prostate cancers." (PMID 32106418, 2020). "For example, although SF3B1 mutations occur at a low frequency (1.1%) in prostate cancer (PCa), SF3B1 mRNA and protein levels are higher in tumor glands than in nontumor adjacent regions." (PMID 32905346, 2020). "The SF3b complex is a component of U2 snRNP and the mutations of the SF3b complex component SF3B1 have been reported in some cancers, including breast and prostate cancers." (PMID 32106418, 2020). "Remarkably, the significance of SF3B1 extends beyond its mutation, as numerous studies have demonstrated a clear link between changes in SF3B1 expression levels and the aggressiveness of various cancers, including prostate cancer, hepatocarcinoma, and diffuse malignant peritoneal mesothelioma 28-40." (PMID 38904016, 2024). "Additionally, we have recently found that SF3B1 is overexpressed and associated with malignant features in prostate cancer and hepatocellular carcinoma, supporting that SF3B1 could represent a valuable therapeutic target in cancer." (PMID 35086552, 2022). "However, the pathological importance of SF3B1 does not only rely on the well characterized role of SF3B1 mutations, but growing evidence indicates that alteration of its expression can also have malignant consequences in some cancers, such as prostate cancer and hepatocarcinoma." (PMID 34857016, 2021). "Furthermore, mutations in SF3B1 have been reported at low frequencies in patients with acute myeloid leukemia, breast cancer, prolactinomas, uveal melanoma, leptomeningeal melanoma, blue nevus-like cutaneous melanoma, pancreatic ductal adenocarcinoma, and prostate cancer." (PMID 37875914, 2023). "Changes in these proteins were found related to myeloid malignancy (u2af2), clinical monoclonal B-cell lymphocytosis (sf3b1), and prostate cancer (usp39)." (PMID 32823483, 2020). "Furthermore, SF3B1 is overexpressed in glioblastoma, hepatocellular carcinoma, prostate cancer, and endometrial cancer." (PMID 37875914, 2023). "Therefore, SF3B2, SF3B1 and the SF3b complex may be good candidates of therapeutic targets, and small chemicals inhibiting/modulating the SF3b complex might be promising for prostate cancer treatment." (PMID 32106418, 2020).
metastatic disease (12 papers, 2017 to 2024). "BAP1 and SF3B1 mutations are found most frequently in metastatic disease, whereas EIF1AX gene mutation is related to a favorable prognosis." (PMID 38175637, 2024). "Mutations in SF3B1 have been correlated with an intermediate potential to develop metastatic disease, occurring later than BAP1 mutations, usually around 7 years after primary treatment." (PMID 39061150, 2024). "UM patients (n = 143 participants) who have SF3B1 mutations exhibited metastatic disease both early and late in their diagnosis, categorized as occurring before or after a follow-up period of 60 months." (PMID 38920653, 2024). "There are currently no medications available that target the YAP-TAZ pathway, which is also active in UM, the cancer-suppressor gene BAP1, or the SF3B1 gene, whose mutations increase the likelihood of metastatic disease." (PMID 37124608, 2023). "There has been increasing attention on the impact of activating genetic mutations in GNAQ and GNA11, loss-of-function mutations in the tumor suppressor gene BAP1, and recurrent mutations at codon 625 of SF3B1 on the advancement of UM towards metastatic disease." (PMID 39061150, 2024). "The clinical significance of this mutation in CM is unknown, whereas in UM, SF3B1 mutation is correlated to late metastatic disease." (PMID 34071371, 2021). "Although BAP1–located on chromosome 3–correlates well with the chromosome 3 status and a BAP1 mutation is associated with a high likelihood for metastatic disease, EIF1AX and SF3B1 occur typically in disomy 3 tumors." (PMID 34439147, 2021). "Furthermore, specific genetic features associated with metastatic disease include loss of chromosome 3 and mutations in the BAP1 (BRCA-associated protein 1) and SF3B1 (encoding splicing factor 3B subunit 1A) genes." (PMID 38175637, 2024). "No patients with EIF1AX or SF3B1 mutations in this cohort are known to have developed metastatic disease with the exception of 2 patients that had co-occurring BAP1 mutations." (PMID 28594900, 2017). "When comparing any aberration with respect to primary and recurrent/metastatic sample types, SF3B1 (Fisher’s exact, P = 0.0057) and SPRED1 (Fisher’s exact, P = 0.02) mutations were mostly present in primary samples and NRAS aberrations were predominantly in recurrent/metastatic tumors." (PMID 31320640, 2019).
myelofibrosis (11 papers, 2018 to 2024). A partial or complete replacement of the bone marrow stroma by fibrous tissue. "Mutations in SF3B1 have been implicated as a common driver mutation in myelodysplatic syndromes (MDS), myelofibrosis and chronic myeloid leukaemia." (PMID 30558566, 2018). "Senin and colleagues described the association between SF3B1 mutations and PV progression to MF; conversely, Tefferi and colleagues did not confirm this result, but they correlated SF3B1 mutations with decreased myelofibrosis-free survival in ET patients." (PMID 36230848, 2022).